CD14 (CD14 molecule)
Diseases named in the same sentence as CD14 in open-access papers (continued):
Sharing a sentence is not in itself a finding about the gene and the disease.
lymphoma (continued). "A minority (<10 %) of CD4 dim CD14 positive monocytes among the lymphoma cells was also documented." (PMID 27567676, 2016). "Furthermore, the increased population of CD14+HLA-DRlow/− cells came mainly from the classical monocyte population in both lymphoma patients and healthy donors." (PMID 26230952, 2015). "However, we observed that the surface expression level of HLA-DR on CD14+ monocytes was decreased in lymphoma patients compared with healthy donors, resulting in an increased population of CD14+HLA-DRlow/− monocytes." (PMID 26230952, 2015). "Similarly, endogenous IL-10 secreted by lymphoma cells also downregulates HLA-DR expression on CD14+ monocytes." (PMID 26230952, 2015). "A subset of MDSC, characterized as monocytic CD14+ cells with low levels of lack of the antigen presenting HLA-DR molecules (CD14+HLA-DRlow/neg (DIM)) has been associated as a negative prognostic factor for survival circulating in the peripheral blood of lymphoma patients." (PMID 35883639, 2022). "Six tissues were common to both genes: 721 B lymphoblasts, CD14+ monocytes, CD33+ myeloid cells, Wholeblood, Lymphoma Burkitts (Raji), and Lymphoma Burkitts (Daudi)." (PMID 40395233, 2025). "A significant increase in the number of all CD14+ monocytes and MHCII− population was reported only in dogs with lymphoma RG." (PMID 36009726, 2022). "The study has shown that in healthy dogs only a small population of CD14+ monocytes lacks the expression of MHCII, whereas in dogs with lymphoma (both NRG and RG) their proportion in relation to MHCII+ monocytes increases." (PMID 36009726, 2022). "An altered immune profile was ascertained in the PB of lymphoma patients characterized by a lower percentage of regulatory NK and CD3+ T-cells, while a significant increase in PMN-MDSCs (CD11b+HLADRdimCD33+CD14−) was observed." (PMID 34441758, 2021). "Specifically, cells isolated from d0 and d28 pi LN biopsy and lymphoma tissue were stained with anti-GPC1 antibody, in conjunction with antibodies directed against CD20, CD3, and CD14, to determine the levels of GPC1+ cell subsets in these tissues." (PMID 32017809, 2020). "In lymphomas, tumor cells release several soluble mediators, leading to continuous B-cell-receptor (BCR) stimulation and T cell and CD14+ monocyte recruitment and through them, to B-cell abnormal proliferation and rescue from apoptosis." (PMID 31934533, 2019). "While in healthy dogs only a small population of CD14+ monocytes lacks the expression of MHCII, in dogs with lymphoma prior to any treatment and in dogs with lymphoma treated with glucocorticoids, the proportion of MHCII− in relation to MHCII+ monocytes is increased." (PMID 36009726, 2022). "Although the numbers of CD14+HLA-DRlow/− monocytes were not significantly different among the subtypes of lymphoma, patients with a higher International Prognostic Index score had statistically a higher percentage of CD14+HLA-DRlow/− monocytes." (PMID 26230952, 2015).
acute myeloid leukemia (19 papers, 2011 to 2025). Acute myeloid leukemia (AML) is a group of neoplasms arising from precursor cells committed to the myeloid cell-line differentiation. "In PMNLs of patients with myelodysplastic syndromes, stem cell malignancies with an increased risk of developing acute myeloid leukemia deficient in formin proteins involved in linear actin polymerization show a specific increase of CD14 messenger RNA." (PMID 33799511, 2021). "The association between let-7a-5p and monocyte differentiation was investigated in the HL-60 acute myeloid leukemia cell line and the macrophage markers CD11b and CD14 were detected by flow cytometry and qRT-PCR." (PMID 29599918, 2018). "However, in acute myeloid leukemia (AML), low SAM levels decrease global DNA methylation, causing increased expression of differentiated myeloid genes (CD11b, CD14) but decreased expression of stemness genes, thereby enhancing differentiation but inhibiting self-renewal in LSCs." (PMID 37370081, 2023). "The presence of myelomonocytic specific markers, such as CD13, CD15, CD33, myeloperoxidase (MPO), CD14, and CD64 is useful for establishing the diagnosis of CD56‐positive acute myeloid leukemia, first presenting in the skin." (PMID 39210931, 2024). "In human acute myeloid leukemia (AML) cell line models, 1,25-dihydroxyvitamin D3 induces monocytic differentiation and CD14 expression, an effect that is mediated through activation of MEF2C signaling via regulation of CCAAT-/enhancer-binding protein alpha (CEBPA)." (PMID 26487643, 2015). "Many different acute myeloid leukemia (AML) cell lines respond to 1,25(OH)2D by increasing CD14 cell surface receptor, some additionally upregulate CD11b and CD11c integrins." (PMID 23213549, 2012). "In acute myeloid leukemia (AML), tumor-derived extracellular vesicles (EVs) activate TLR2 signaling on monocytes via their surface palmitoylated proteins, inducing their differentiation into immunosuppressive CD14+HLA-DRlow MDSCs." (PMID 40977744, 2025). "Acute myelogenous leukaemia M5-like were typified by the demonstration of markers of mature monocytes CD64 and/or CD14, and lack of immature markers." (PMID 39968161, 2025). "Likewise, we were not able to detect CD209+CD14+CD163+ ercDCs among PBMC of healthy donors or patients by flow cytometry (data not shown) and the ercDC score was very low in samples of acute myeloid leukemia of the TCGA collection compared to ccRCCs (not shown)." (PMID 36291154, 2022).
AIDS (19 papers, 2008 to 2026). A syndrome resulting from the acquired deficiency of cellular immunity caused by the human immunodeficiency virus (HIV). "sCD14 has been used as a surrogate marker for integrity of the gut mucosal barrier, which is lost during progression to AIDS in pathogenic infections, and levels of soluble CD14 in HIV-1 infected humans predicts rate of disease progression." (PMID 26360709, 2015). "The positive correlation observed between CD14+ macrophages and plasma LPS suggests that the increased frequency of these cells in the colon of AIDS patients is linked to MT." (PMID 26475133, 2015). "AIDS trial: A pilot study has shown that aspirin has an effect on CD14 cells causing a delay in the shift towards the development of AIDS symptoms." (PMID 24678343, 2014). "This polymorphism has been linked to differences in CCR5 expression levels on CD14+ monocytes and has known association with the rate of progression to AIDS." (PMID 20206716, 2010). "Given that high levels of secreted CD14 have been associated with impaired responses to LPS, it has been proposed that the release of general immunosuppressant IL-10 by monocytes facilitates the progression to AIDS." (PMID 19486514, 2009). "We have demonstrated that the colon of cotrimoxazole-treated ART-naïve AIDS patients contains increased numbers of activated CD14+ pro-inflammatory macrophages and that these cells are responsive to bacterial LPS and linked to MT." (PMID 26475133, 2015). "Studies are also needed to assess the phagocytic properties of CD14+ macrophages in the colon of African AIDS patients." (PMID 26475133, 2015). "Ex vivo studies of total MMC (containing CD14+ macrophages) isolated from the colon of AIDS patients indicated that these cells secreted increased levels of TNF-α, IL-6, CCL2 and CXCL10 compared to HIV-negative controls." (PMID 26475133, 2015). "As in CD, there was a marked increase in CD14+ macrophages in the colon of AIDS patients compared to HIV-negative controls." (PMID 26475133, 2015). "It has recently been described that increased activation and rapid turnover of monocytes, in particular those with a CD14+CD16+ phenotype, associates with macrophage destruction in tissues and predicts the tempo of progression to AIDS in SIV-infected RMs." (PMID 25356757, 2014). "Bregs, CD8+CD20+ T-cells, CD8+CD14+ T-cells, and M2-like CD14+CD163+ monocytes may serve as early indicators of immune dysfunction in PWH at risk for developing AIDS-NHL, potentially months to years before diagnosis, as this cohort study suggests." (PMID 41148820, 2025). "Additionally, a recent multicenter AIDS cohort study found that PWH had higher plasma levels of soluble CD14, a marker of classical monocytes that are precursors to M1 macrophages, which contain lower amounts of opioid peptides than M2." (PMID 37371035, 2023). "Persistent monocyte activation may be of great concern for HIV-infected children, since soluble CD14 has been proposed as an independent predictor of mortality as well as subsequent non-AIDS events (e.g., cardiovascular disease) in adults with HIV." (PMID 29623447, 2018). "The absolute number of CD14+ cells, as determined by IHC, increased from 1.8 cells/HPF in controls to 55 cells/HPF (p = 0.004) in patients with AIDS; the percentage of CD14+ cells, as assessed by flow cytometry using CD33, increased from a median 6.5 to 21.2 % (p =0.007)." (PMID 26475133, 2015). "Phenotypic and functional characterization of intestinal macrophages indicated that there was marked a increase in a unique subset of pro-inflammatory (CD14+) mononuclear phagocytes in the colon of cotrimoxazole-treated ART-naïve AIDS patients compared to uninfected controls." (PMID 26475133, 2015).
AIDS (continued). "Collectively, these findings indicate that macrophages in the colon of African AIDS patients with diarrhea and/or weight loss have an activated CD14+ phenotype and express pro-inflammatory cytokines (TNF-α, IL-1β) that are known to be induced by LPS–mediated activation of CD14+ macrophages." (PMID 26475133, 2015). "Furthermore, up-regulation of IL-10 production in HIV/AIDS patients has been correlated with increased levels of monocyte-secreted myeloid differentiation-2 and soluble CD14; both proteins are key molecules in the immune recognition of gram-negative bacterial lipopolysaccharide (LPS)." (PMID 19486514, 2009). "In this study, we performed a comprehensive analysis of miRNA expression in three immune populations, namely, CD14+ monocytes, neutrophils, and CD8+ T cells, in multiple sclerosis (MS) and type 1 diabetes (T1D), two prototypical AIDs." (PMID 41948457, 2026). "This study aimed to identify and characterize CD3+ T-cells and CD14+ monocytes in the circulation of PWH, focusing on HIV-positive cART-naïve individuals who went on to develop AIDS-NHL within 3 to 36 months prior to their diagnosis (pre-NHL)." (PMID 41148820, 2025). "Macrophages isolated from AIDS patients also had an increased ability to respond to microbial products including LPS, a TLR4 ligand, presumably due to the upregulation of CD14 and other innate response receptors." (PMID 26475133, 2015). "HIV and SIV DNA and RNA are found in both CD14+CD16− and CD14+CD16+ monocyte subsets in acute infection and AIDS." (PMID 21494695, 2011). "We found that some transgenic (Tg) mouse models of AIDS also develop accumulation of mature and immature cells of the granulocytic lineage, decreased erythroid precursors, and expansion of MDSC (equivalent to human CD14+ CD16+ cells)." (PMID 34106001, 2021). "In addition to CD14, CD33+ macrophages in AIDS patients co-expressed the Fc receptor γ (CD16) and T cell the co-stimulatory molecules CD80 and CD86." (PMID 26475133, 2015). "We thank the NIH AIDS Research and Reference Reagent Program for the IL-2, cell lines and HIV lab strains and Dr. Larry Wahl to kindly provide elutriated CD14+ monocytes and CD14− cells counterpart." (PMID 22912740, 2012). "Total unfractionated mucosal mononuclear cells (MMC) isolated from the colon of AIDS patients, but not MMC depleted of CD14+ cells, secreted increased levels of proinflammatory cytokines ex vivo in response to LPS." (PMID 26475133, 2015). "In minocycline treated animals we did not observe an expansion of CD14+CD16+ and CD14loCD16+ monocytes that was observed in untreated animals with AIDS." (PMID 21494695, 2011).
bacterial sepsis (19 papers, 2009 to 2025). "Retrospective blood analysis revealed high levels of soluble CD14 subtype, a bacterial sepsis marker known as presepsin." (PMID 40419900, 2025). "Presepsin/sCD14-ST is considered a highly specific bacterial sepsis marker that is mainly produced and secreted by monocytes after bacterial phagocytosis and intracellular cleavage of CD14." (PMID 40419900, 2025). "For example, a distinct CD14+ monocyte cluster is expanded in bacterial sepsis and can function as a marker for distinguishing case–control states." (PMID 37919720, 2023). "Impaired phagocytic and antigen-presenting capacity of CD14+CD16+ cells has also been described in bacterial sepsis." (PMID 28369200, 2017). "Recently, CD14 inhibition is known to efficiently attenuate early inflammatory response in bacterial sepsis." (PMID 23565251, 2013). "The strong activation of TLR2 and CD14 was also observed in murine brain parenchyma after the presence of S. suis bacteremia." (PMID 20937098, 2010). "We previously reported an expanded CD14+ monocyte state, MS1, in patients with bacterial sepsis and validated expansion of this cell subpopulation in publicly available transcriptomics data." (PMID 34103408, 2021).
colitis (19 papers, 2011 to 2024). Inflammation of the colon. "Furthermore, mice with MyD88-deficient TECs, which exhibit a deficiency in the recruitment of CD14+moDC, also suffer from a decreased thymic Treg output and functionality, which renders the peripheral T cell repertoire prone to colitis induction." (PMID 32398640, 2020). "Thus, CD14-deficiency results in a faster and stronger colitis development." (PMID 26637175, 2015). "DCs exhibited the lowest M1 and M2 scores, while mono- and inflammatory macrophages displayed higher M1 scores, indicating the dominance of pro-inflammatory macrophages during colitis (related to Il1b, Irf1, Cd14, Fcgr3 expression level)." (PMID 38674054, 2024). "Despite being both forms of TNF detrimental for the course of colitis, the expression of mTNF by CD14 + macrophages has been reported to be relevant in IBD17, and mTNF signaling has been implicated in the development of granulomas in CD patients." (PMID 35705557, 2022). "Although limited data exists thus far on monocyte dynamics in tissue during irAEs, early analyses of colitis patients point to an influx of monocytes with a phenotype resembling that of the CD14+ population reported here." (PMID 36358824, 2022). "Experimental colitis colonic and peritoneal macrophages and human CD14+ monocytes have been reported to express EGFR, but we did not detect EGFR expression in Ana-1 and THP-1 cells here." (PMID 27683110, 2016). "In 1.5% DSS treated Cd14-/- mice elevated TINT time intervals were observed beginning from day 5 post colitis-induction sustaining on the same level until the end of the experiments." (PMID 26637175, 2015). "In contrast to this, clinical scoring of Cd14-/- mice revealed a significantly higher score of nearly 6 on day 7 post colitis-induction." (PMID 26637175, 2015). "Correlating to this the reduction of body weight reached a maximum of ~10% on day 7 post colitis-induction in WT mice and ~15% in Cd14-/- mice." (PMID 26637175, 2015). "Elevated TINT time intervals were detected in DSS treated Cd14-/- mice compared to WT mice reliably detecting CD14 dependent differences in colitis severity." (PMID 26637175, 2015). "On day 7 post colitis-induction Cd14-/- mice demonstrated significantly higher TINT time intervals than the respective WT mice." (PMID 26637175, 2015). "Subsequent clinical scoring revealed a maximum score of 5 on day 7 post colitis-induction in WT mice but a significantly higher score of nearly 7 in Cd14-/- mice." (PMID 26637175, 2015). "WT as well as Cd14-/- mice treated with 1% DSS demonstrated on day 5 post colitis-induction a slightly increased clinical score." (PMID 26637175, 2015). "TINT time intervals were elevated in Cd14-/- mice treated with 1% DSS beginning from day 5 post colitis-induction and increased slightly until the end of the experiments." (PMID 26637175, 2015). "Consistently, the cellularity of CD14+moDC is diminished in mice with MyD88-deficient TECs, in which the frequency and functionality of thymic CD25+Foxp3+ Tregs are decreased, leading to aggravated mouse experimental colitis." (PMID 32398640, 2020). "During the onset of DSS-induced colitis, CD14/TLR4:LPS-dependent interaction between macrophages and bacteria, which have passed through DSS-injured colonic epithelium, results in the activation of NLRP3 inflammasome, which leads to the enhanced production of IL-1β in colonic macrophages." (PMID 31336879, 2019). "Furthermore, CD14 has been shown to be protective in experimental colitis and that the predominant form of CD14 in the gut is sCD1418,21,22." (PMID 29335601, 2018). "Previously, CD14 was identified as a modifier gene for colitis with likely protective properties." (PMID 26637175, 2015). "Colitis was induced with 1% or 1.5% DSS in group-housed WT and Cd14-deficient mice." (PMID 26637175, 2015).
colitis (continued). "For Cd14, which is involved in the detection of lipopolysaccharides by TLR4, it was later demonstrated that a higher expression by gut epithelial cells is responsible for a lower colitis susceptibility in IL-10-/- mice with a C3H than with a C57BL/6 background." (PMID 23951309, 2013). "The CD14 surface expression was increased in MPTP-treated rats without colitis, but it decreased in both saline- and MPTP-treated rats with colitis." (PMID 34884737, 2021). "Focussing on the innate immune profile, the expansion of HLA-DR+CD14+CD16– cells was observed in those who developed colitis, with values reaching significance in responders but not in nonresponders." (PMID 36173679, 2022). "These CD14 dependent differences in colitis severity were mirrored not only when applying the clinical score and measuring the body weight, but also when the TINT test was performed." (PMID 26637175, 2015). "Cd14 has been identified as a genetic modifier of experimental IBD whose expression level determines protection from disease and whose genetic deletion aggravates colitis." (PMID 26637175, 2015). "Therefore, TINT is an easily applicable method for severity assessment in a mouse colitis model detecting CD14 related differences, but not dose dependent differences." (PMID 26637175, 2015).